EGF (epidermal growth factor)
Diseases named in the same sentence as EGF in open-access papers (continued):
Sharing a sentence is not in itself a finding about the gene and the disease.
tumor (continued). "Once activated by extracellular signals such as EGF, c-Src acts as a common upstream regulator of multiple oncogenic pathways, including the Ras/MAPK and PI3K/AKT pathways, thereby inducing tumor progression." (PMID 24244675, 2013). "Nuclear localization of CCN, EGF/EGFR and FGF/FGFR is often detected in cancer cells, in correlation with tumor progression." (PMID 24340049, 2013). "At the time of the recurrence, approximately one gram of the tumor tissue was enzymatically dissociated, and cell aggregates or spheres were allowed to form in serum free medium containing FGF and EGF in suspension culture." (PMID 23527265, 2013). "Quantization of EGF-NIR in tumors, normalized to skeletal muscle and compared to its level in the liver, indicated a faster accumulation of the agent in the tumor, compared to liver, suggestive of a specific EGFR mediated process." (PMID 23857061, 2013). "Subsequently, The TAM will secrete growth factors such as EGF, TGFβ, FGF, VEGF, IL1, TNF and IL6 that promote tumor cell proliferation, invasion and metastasis." (PMID 23874655, 2013). "DPP9 can influence antigen processing, epidermal growth factor (EGF)-mediated signaling and tumor biology." (PMID 24223149, 2013). "In order to design a peptide with higher receptor affinity but preserving the anti-tumour properties of PCI, EGF and PCI structures were superimposed." (PMID 23935985, 2013). "Several studies have shown that EGF, by activating EGFR, leads to increased cell migration, a feature of tumour progression, metastasis and wound healing but in other cell-types leads to increased cell proliferation." (PMID 23593160, 2013). "Among the tumor supportive factors potentially secreted by TAMs, TGF-β, EGF, and HGF/SF have drawn the most attention, though dissecting the precise role of TAMs in the production of these trophic factors remains to be accomplished." (PMID 23737783, 2013). "EGF is well known to activate signaling pathways, such as ERK1/2 and PI3K-Akt, to regulate cell proliferation, survival and differentiation in various tumor cell models." (PMID 24069372, 2013). "Fibroblasts produce a number of growth factors (including FGF, EGF, PDGF, and TGF-β), and ECM components (such as collagen, elastin and proteoglycans), which serve in wound and tumor stroma formation." (PMID 24274644, 2013). "The TNFα + Estrogen + EGF stimulation has endowed the cancer cells with high spreading and EMT characteristics and with tumor- and metastasis-promoting functions." (PMID 24369447, 2013). "Further supporting the ability of TNFα + Estrogen + EGF stimulation to induce EMT was the prominent increase in the expression of the known EMT activators Zeb1, Snail, and Slug in the tumor cells (the EMT regulator twist was down-regulated; data not shown)." (PMID 24369447, 2013). "Here, we report the finding that treatment with EGFR inhibitors of various tumor cells, when stimulated with hepatocyte growth factor (HGF) and EGF, results in transient upregulation of phosphorylated AKT." (PMID 23812422, 2013). "The majority of existing targeting agents focus on both EGF/VEGF and their receptors, but more recent research has revealed many new pathways related to tumor angiogenesis and proliferation, providing numerous new potential targets." (PMID 24216699, 2013). "Since previous studies suggested the involvement of isoform shift from 3 to 1 in carcinoma progression, we treated cells with tumor stimulus (TGF-β, EGF and TNF-α) that facilitate the progression and examined the shift." (PMID 23936352, 2013). "In NSClines, HGH induces the strongest chemotactic response from a variety of multiple tumor-derivedgrowth factors including vascular endothelial growth factor (VEGF), epidermal growth factor (EGF)and transforming growth factor alpha (TGF-α)." (PMID 23637756, 2013).
tumor (continued). "Exogenous signals such as epidermal growth factor (EGF) and hepatocyte growth factor (HGF) were previously reported to be vital to maintain sustained growth of tumor cells by binding to their receptors." (PMID 24205104, 2013). "The EMT program can be activated by a multitude of factors secreted by tumor stroma cells, which triggers a complex signaling network including TGF-β, Wnt, HGF, EGF, and PDGF pathways." (PMID 23898462, 2013). "The tumor uptake after injection of other macromolecular conjugates, like EGF and VEGF, also showed similar trend in different tumor size." (PMID 23675454, 2013). "In bone metastasis, acting as a sheddase, ADAMTS1 promotes the release of membrane bound epidermal growth factor (EGF)-like growth factors, including amphiregulin (AREG), heparin-binding EGF (HB-EGF), and transforming growth factor α (TGFα) from tumor cells." (PMID 24213506, 2012). "The aim of the present study was to explore the usefulness of near infrared-labeled EGF (EGF-NIR) for bio-imaging of CRC using in vitro and in vivo orthotopic tumor CRC models and ex vivo human CRC tissues." (PMID 23144978, 2012). "The measurements of EGF-NIR in the tumors normalized to skeletal muscle and compared to the liver, indicated a faster accumulation of the agent in the tumor, compared to the liver, supporting the possibility of a specific EGFR- mediated process." (PMID 23144978, 2012). "We found relatively high SBRs for EGF-NIR binding to the whole animal and isolated tumors, supporting the notion that EGF-NIR is a suitable imaging agent for CRC tumor visualization using NIR endoscopy." (PMID 23144978, 2012). "The expressions of numerous cytokines that are growth factors for tumor cells such as interleukin 1β (IL-1β); tumor necrosis factor (TNF); epidermal growth factor (EGF) and IL-6 are also regulated by NF-κB." (PMID 22873280, 2012). "We also know from investigations of the relationship between PTPRJ and EGFR, that one proposed tumour suppressive mechanism for DEP-1 is the inactivation and retention of EGFR at the cell membrane and therefore the abrogation of EGF-induced signaling." (PMID 22815804, 2012). "Selective accumulation of EGF-NIR as evident from in vivo competition with cetuximab, was clearly seen after 24 and 48 hours in the tumor and EGFR positive organs such as the liver." (PMID 23144978, 2012). "HCV chronic infection can induce chaotic cellular signalling, raising tumour cells with activation of epidermal growth factor (EGF) and NF-kB, contributing to tumour development and survival of infected cells." (PMID 23206959, 2012). "Monoclonal antibodies against HER1 and HER2 as well as EGF, the natural ligand of HER1, have been successfully used as targeting moieties for the design of anti-tumor contrast agents based on QDs." (PMID 23133578, 2012). "The surface of the lipoproteins can be modified to target epidermal growth factor (EGF) or folate receptors, overexpressed in different tumour cells." (PMID 22576228, 2012). "In this study, we first tested three cytokines (TGF-ß, TNF-α, and EGF) for the EMT induction of A549 and Panc-1 cells, analyzing expression of some tumor invasion markers as well as EMT markers." (PMID 23300891, 2012). "As we previously demonstrated that EGF-Cy5.5 uptake into the OSCC cells was mediated by EGFR, the fluorescence signal intensity was proportional to EGFR expression of tumor cells." (PMID 23029451, 2012). "Epidermal growth factor (EGF) signaling via the EGFR is a known inducer of cell proliferation and tumor cell invasion." (PMID 22194989, 2011). "Because of EGF-SEA containing an E-tag peptide, positive tumor cells and T cells were also found using anti-E-tag IgG detection (data not shown)." (PMID 21311755, 2011). "Here by using fusion with EGF to target SEA (D227A) to the solid tumor, it becomes possible to retain tumor-unspecific T lymphocytes in the tumor site." (PMID 21311755, 2011).
tumor (continued). "We measured the concentration of growth factors, VEGF, EGF, FGF basic and G-CSF, in tumor sphere culture media at different time points." (PMID 22192404, 2011). "We analysed mRNA transcript expression levels of EGFR ligands (EGF and TGF-α) and two isoforms of the ErbB3 ligand, NRG-1 (NRG-1α and NRG-1β) in each one of those two tumour compartments." (PMID 21792199, 2011). "BALF from tumor-bearing lungs contained 3.5-times more IGF-1 than BALF from naïve mice, while EGF levels were unchanged." (PMID 21699731, 2011). "In addition to the potential use of Gefitinib / PIM kinase inhibitor combination in the treatment of CRPC, this combination may be especially attractive in treatment of EGF driven tumours such as NSCLC in which Gefitinib as a single agent already has significant activity." (PMID 22193779, 2011). "In mice treated with EGF-SEA, CD4+, CD8+ and SEA-reactive T lymphocytes were enriched around the EGFR expressing tumor cells." (PMID 21311755, 2011). "We further show that the stem-cell culture cytokines EGF plus FGF-2 activate DNA repair and thus confound in vitro comparisons of DNA damage repair between stem-like and more differentiated tumor cells." (PMID 21663643, 2011). "EGF-SEA strongly suppressed solid tumor growth (control versus EGF-SEA, mean tumor weight: 1.013 versus 0.197 g, difference = 0.816 g, 95% confidence interval [CI] = 0.54 to 1.37, p<0.001), and had a slight influence on the spleen measured by weight." (PMID 21311755, 2011). "Once EGF-SEA-promoting infiltrating CTLs accumulated in the tumor site, the tumor became apoptotic by an in situ attack." (PMID 21311755, 2011). "The findings demonstrate that antibody-like EGF-SEA plays an important role in arresting CTLs in the solid tumor site and has therapeutic potential as a tumor-targeting agent." (PMID 21311755, 2011). "Tumor tissues were dissociated mechanically into a single cell suspension and were cultured in serum-free DMEM/F12 medium supplemented with EGF and bFGF." (PMID 21342503, 2011). "The AP-1 complex can respond immediately to many different extracellular stimuli, such as tumor-promoting TPA, epidermal growth factor (EGF), and serum." (PMID 20955608, 2010). "The invasiveness of tumor cells is also stimulated by epidermal growth factor (EGF) synthesized by TAM in response to tumor-derived CSF-1, leading to the induction of several genes involved in the migration of tumor cells." (PMID 20822533, 2010). "We further demonstrate that the microenvironment provided by the tumor stimulated MSC directly to enhance the growth of Skov-3, which is significantly enhanced by growth factors interleukin-6 (IL-6) and EGF." (PMID 19352430, 2009). "S9 abrogated EGF-activated PI3K-Akt-mTOR signaling cascade and Akt translocation to cellular membrane in human tumor cells." (PMID 19293927, 2009). "The fourth and final characteristic that defines a TAF is secretion of tumor-supportive growth factors, including HGF, EGF and IL6." (PMID 19352430, 2009). "Macrophages recruited to hypoxic sites exert a tumor-promoting effect through the expression of genes with mitogenic, angiogenic, and migration/invasion stimulating properties, such as VEGF, EGF, or HGF." (PMID 19536297, 2009). "Further analyses are required to determine the relative contributions of EGF-, FGF- and PDGF-induced signaling on suppression of miR-124 and miR-137 transcription in adult NSCs and GBM tumor stem cells." (PMID 18577219, 2008). "The epidermal growth factor (EGF) and EGF receptor (EGFR) families play important roles in the hyperplastic growth of several tissues as well as tumor growth." (PMID 18439312, 2008). "We demonstrate the migration of MSC towards growing normal and tumour cells, as well as to platelet-derived growth factor (PDGF), epidermal growth factor (EGF), and vascular epidermal growth factor (VEGF)." (PMID 18665180, 2008).
tumor (continued). "Our study shows the migration of MSC towards growth factors secreted by growing tumour and normal cells, with PDGF as most potent chemoattractant, followed by EGF and VEGF, in line with recent findings." (PMID 18665180, 2008). "Further investigation of the intracellular signalling pathways involved in the hEGR1 induction by EGF and its inhibition by gefitinib would clarify the role of hEGR1 in EGFR-dependent tumour growth and progression and its inhibition by gefitinib." (PMID 17311025, 2007). "It is well documented that tumor cells synthesize and respond to growth factors such as EGF, FGF, and PDGF, and that NSAIDs negatively regulate the EGF/PDGF pathway with evidence of crosstalk between COX-2 and EGFR." (PMID 17156488, 2006). "In an in vitro study, these two types of EGFR mutants demonstrated an enhanced TK activity in response to EGF and increased sensitivity to inhibition by TKI, although the biological activity between tumours with L858R and those with deletions was different." (PMID 16552419, 2006). "To date, the other clinically available molecular-targeted agents target one of two key growth factors crucial for tumour growth and development, vascular endothelial growth factor (VEGF) and EGF, as do many of the agents currently in development." (PMID 15928655, 2005). "Tumor cell growth in response to growth factors, such as Heregulin (HRG), epidermal growth factor (EGF), or insulin-like growth factor-1 (IGF-1), was also studied." (PMID 16168116, 2005). "Instead, there was a good correlation between EGFR expression (or EGF-induced JNK activation) and drug resistance among ovarian and germline tumour cells." (PMID 15655552, 2005). "ZD6474 selectively targets two key pathways in tumour growth by inhibiting vascular endothelial growth factor (VEGF)-dependent tumour angiogenesis and epidermal growth factor (EGF)-dependent tumour cell proliferation and survival." (PMID 15928653, 2005). "In vitro experiments demonstrate that EGF stimulation of EGFR-positive NSCLC cell lines can result in the upregulation of MMP-9 and, likewise, inhibition of EGFR in vivo reduces tumour cell MMP-9 expression." (PMID 15365565, 2004). "In the clinical setting, it will be important to define tumours whose growth is dependent on the EGFR and which are being driven by activating ligands such as TGFα and EGF." (PMID 11875715, 2002). "Receptor analyses demonstrated high-affinity binding sites for epidermal growth factor (EGF) and insulin-like growth factor I (IGF-I) on the membranes of H69 and H157 tumours." (PMID 7947094, 1994). "A method to determine the binding of epidermal growth factor (EGF) to the particulate fraction of the cell has been established and evaluated using rat liver, human placenta, and tumours of human breast and brain." (PMID 2021539, 1991). "Other circulating miRNAs upregulated in ESCC include miR-25, which supports tumor progression by repressing several tumor-suppressor genes and activating the TGF-β, VEGFA/VEGFR, EGF/EGFR, and Wnt/β-catenin signaling pathways, which are fundamental for angiogenesis and metastasis." (PMID 41596525, 2026). "Upon systemic administration in an A549 xenograft mouse model, EGF-Exo-DOX exhibited enhanced accumulation in tumors relative to the heart, with minimal cardiac accumulation, significantly reducing tumor burden, mitigating DOX-induced cardiotoxicity, and exhibiting no tumorigenic effects." (PMID 41593600, 2026). "Upon degranulation, they release potent proangiogenic factors, including vascular endothelial growth factor (VEGF), fibroblast growth factor (FGF), epidermal growth factor (EGF), and platelet-derived growth factor (PDGF), which collectively drive neovascularization and sustain tumor growth." (PMID 41601669, 2026). "They secrete pro-angiogenic factors, as VEGF, EGF, PDGF, TGF-β, that initiate neovascularization, as well as matrix metalloproteinases, such as MMP-2, MMP-9, which remodel extracellular matrix in favor of tumour cell invasion." (PMID 41476776, 2026).
tumor (continued). "EGF labeled with QDs (EGF-QDs) in complex with the receptor was effectively internalized both in tumor-derived and enMSC cells, and deacidification did not inhibited this process." (PMID 41155514, 2025). "The differentiation of CAFs is crucial for cancer initiation and progression, and it is regulated by signaling pathways induced by tumor cell-derived TGF-β, EGF, PDGFα, PDGFβ, basic fibroblast growth factor (bFGF, also known as FGF2), interleukin 6 (IL-6), and interleukin 1β (IL-1β)." (PMID 40750884, 2025). "PCBs’ binding to EGF, as observed in our docking results, may stabilize EGFR-EGF interactions, prolonging MAPK/ERK and PI3K-Akt signaling, which drives proliferation and metabolic adaptation in tumor cells." (PMID 40584614, 2025). "Their activation within the TME is driven by tumor-secreted factors such as transforming growth factor-β (TGF-β), platelet-derived growth factor (PDGF), hepatocyte growth factor (HGF), and epidermal growth factor (EGF)." (PMID 40649958, 2025). "Moreover, monocytes can also promote tumor growth and angiogenesis by releasing VEGF, epidermal growth factor (EGF), and tumor necrosis factor-α (TNF-α)." (PMID 40265015, 2025). "Moreover, EGF-driven EGFR activation also up-regulated CD274, suggesting a role for HER family signaling in promoting immunosuppression within the tumor microenvironment." (PMID 40642068, 2025). "Furthermore, TGF-α and EGF signaling drive epithelial-to-mesenchymal transition (EMT), a process that enhances tumor cell motility, invasion, and resistance to chemotherapy." (PMID 40596459, 2025). "Similarly, tumor cells can recruit and activate stromal cells such as CAFs into the tumor microenvironment through secretion of pro-fibrotic growth factors such as TGF-α, TGF- β, FGF-2, and EGF." (PMID 41199904, 2025). "Further growth factors, such as insulin like growth factor (IGF-1), epidermal growth factor (EGF) and TGFα might also present an autocrine action relevant for tumor proliferation, as their receptors are present in NEN." (PMID 40214893, 2025). "Notably, the EGF, MK, and TWEAK signaling pathways were more actively engaged in high-glycan score tumor cells than in low-glycan score cells." (PMID 40861802, 2025). "Targeting moieties such as folic acid, biotin, arginylglycylaspartic acid (RGD) and epidermal growth factor (EGF) peptides, carbohydrates, and amino acids have been employed to exploit overexpressed receptors in tumors, enhancing cellular uptake and tumor accumulation." (PMID 40807472, 2025). "In addition, CAFs secrete EGF and maintain the expression of integrin α5 (ITGA5) on HGSOC ascites tumor cells (ATCs)." (PMID 40369674, 2025). "Anti-angiogenic agents target various regulators engaged in tumor angiogenesis (i.e., VEGF, fibroblast growth factor (FGF), PDGF, epidermal growth factor (EGF), TGF-β, HIF1, NF-κB, MMPs, and integrins), with the VEGF and its receptor VEGFR signaling pathway playing a dominant role in this process." (PMID 39849659, 2025). "Furthermore, TFPI2 may promote M2-type tumor-associated macrophages (TAMs) via PPARγ, which support tumor growth through immune evasion, angiogenesis, and ECM remodeling by releasing factors like epidermal growth factor (EGF), hepatocyte growth factor (HGF), VEGF, MMPs, IL-10, and TGF-β." (PMID 40361374, 2025). "Notably, pro-tumor pathways including TNF, EGF, VEGF, FGF, and WNT are enriched in the NT5E-positive group." (PMID 41487509, 2025). "Meanwhile, TAMs foster cancer progression by interacting with TME or by secreting growth factors such as epithelial growth factor (EGF), platelet-derived growth factor (PDGF), TGF-β, hepatocyte growth factor (HGF), basic fibroblast growth factor (bFGF) that stimulate tumor proliferation." (PMID 40083710, 2025).